APOBEC3G (apolipoprotein B mRNA editing enzyme catalytic subunit 3G)
Diseases named in the same sentence as APOBEC3G in open-access papers (continued):
Sharing a sentence is not in itself a finding about the gene and the disease.
breast carcinoma (10 papers, 2015 to 2024). "The depletion of Exosc9 induces excess APOBEC3G mRNA expression and, subsequently, reduces P-body formation and stress resistance in breast cancer cells." (PMID 37887339, 2023). "We examined APOBEC3A, APOBEC3B and APOBEC3G mRNA expression levels in a panel of 15 breast cancer cell lines (five luminal, five basal and five HER2+) by quantitative PCR." (PMID 27634334, 2016). "While for other APOBEC members, including APOBEC3D, APOBEC3F, and APOBEC3G, they show DNA hyper-methylation in ER− breast cancer cells when compared to HMEC (P < 0.01, Wilcoxon signed rank test)." (PMID 26682542, 2015). "We constructed a risk model based on the expression levels of these RBPs and found that ADAT2, C2orf15, SRP72, PAICS, RBMS3, APOBEC3G, NOA1, and ACO1 could be used for risk assessment in terms of breast cancer prognosis." (PMID 38783078, 2024). "In addition, APOBEC3G (apolipoprotein B mRNA-editing enzyme, catalytic polypeptide-like 3G) is involved in RNA editing, and deletion in APOBEC3 gene has been correlated to breast cancer risk." (PMID 30922380, 2019). "By further analysing above EMT-related RBPs and AS in breast cancer tissues in TCGA, it was found that the expression levels of ADAT2, C2orf15, SRP72, PAICS, RBMS3, APOBEC3G, NOA1, ACO1 and the AS of TNC and COL6A3 were significantly correlated with the prognosis of breast cancer patients." (PMID 38783078, 2024). "For other APOBEC family members, they show either extremely low (median log2-transformed RPKM < 0) mRNA levels (including APOBEC3A, APOBEC3H, APOBEC1, APOBEC2, APOBEC4, and AICDA), or no obvious expression differences between ER+ and ER− breast cancers (including APOBEC3D, APOBEC3F, and APOBEC3G)." (PMID 26682542, 2015).
lymphoma (9 papers, 2015 to 2025). A malignant (clonal) proliferation of B- lymphocytes or T- lymphocytes which involves the lymph nodes, bone marrow and/or extranodal sites. "Expression of APOBEC3G in lymphoma cells associates with efficient DSB repair, whereas inhibition of APOBEC3G expression or deamination activity results in impaired joining of DSBs by NHEJ, implying a prosurvival role of APOBEC3 in lymphoma cells." (PMID 26097867, 2015). "APOBEC3G, an endogenous RNA editing enzyme, is highly expressed in cytotoxic lymphocytes and has been identified in primary natural killer cells and lymphoma cell lines." (PMID 41446042, 2025). "G>A SNVs have been reported to be the most common SNVs in the proviral genomes of patients with adult T-cell leukemia/lymphoma and carriers of HTLV-1, and the G>A SNV is associated with the cellular antiviral restriction factor human Apobec3G." (PMID 39080643, 2024). "APOBEC3G is an endogenous RNA editing enzyme in primary natural killer cells and lymphoma cell lines." (PMID 30791937, 2019). "Here, we show that the related cytidine deaminase, APOBEC3G, induces site-specific C-to-U RNA editing in natural killer cells, lymphoma cell lines, and, to a lesser extent, CD8-positive T cells upon cellular crowding and hypoxia." (PMID 30791937, 2019). "Recent reports have shown that APOBEC3G enhances lymphoma cell radioresistance by promoting DNA repair." (PMID 28903341, 2017). "Notably, APOBEC3G induces site-specific C-to-U RNA editing in natural killer cells and lymphoma cell lines under crowded and hypoxic conditions." (PMID 41446042, 2025). "APOBEC3G has been shown to enhance lymphoma cell radioresistance by promoting DNA repair." (PMID 28903341, 2017). "However, in lymphoma cells APOBEC3G has been shown to enter the nuclear compartment as part of a DNA damage response and promote DNA repair by activating the ataxia telangiectasia mutated (ATM) DNA damage checkpoint kinase." (PMID 27634334, 2016). "Although more research is needed, we speculate that whereas replication stress-induced APOBEC3B regulation could contribute to a portion of APOBEC3-mediated mutagenesis, APOBEC3G upregulation could enhance DNA repair, as has been previously postulated in lymphoma cells." (PMID 27634334, 2016). "Additionally, APOBEC3G acts as a prosurvival factor in lymphoma cells." (PMID 26097867, 2015).
pancreatic cancer (7 papers, 2015 to 2023). "Thus, a high expression of lncRNA H19 and APOBEC3G may be considered as novel diagnostic markers in pancreatic cancer and sulforaphane analogues may be suited for the development of new and effective drugs for treatment of PDAC and other tumor entities." (PMID 33669381, 2021). "APOBEC3G knockdown with siRNA showed an increased radiosensitivity in several cancer cell lines, including pancreatic cancer MIAPaCa2 cells and lung cancer A549 cells." (PMID 35563460, 2022). "As an important member of the APOBEC family, APOBEC3G plays a pivotal role in liver, colorectal, prostate, pancreatic cancer, and myeloma by affecting single-stranded DNA (ssDNA) that is exposed during replication, transcription, or during DNA damage repair." (PMID 36144542, 2022). "Here, we found that APOBEC3G (A3G) was up-regulated in pancreatic cancer and promoted tumor formation in vivo." (PMID 26178819, 2015). "APOBEC3G, for example, has been found at high levels in colon and pancreatic tumors." (PMID 36978147, 2023). "As a virus-induced protein, APOBEC3G (A3G) presents extensive anti-virus ability, but the role of A3G in pancreatic cancer was previously unknown." (PMID 26178819, 2015). "APOBEC3s can also inhibit cell death via multiple mechanisms: APOBEC3G was shown to inhibit anoikis via Akt activation in pancreatic cancer, and APOBEC3B may decrease cell death in gastric cancer by inhibiting PDCD2 function and lowering ATM and Chk1/2 activity." (PMID 36978147, 2023). "In conclusion, our data provide strong evidence for H19-mediated APOBEC3G expression, which in turn activates TGF-β/Smad2 signaling and thereby contributes to the progression of pancreatic cancer, and this process is inhibited by sulforaphane." (PMID 33669381, 2021).
colorectal cancer (5 papers, 2012 to 2023). A primary or metastatic malignant neoplasm that affects the colon or rectum. "In colorectal cancer, APOBEC3G tissue protein expression was associated with poor prognosis and suggested to be mechanistically involved in the formation of liver metastasis." (PMID 36204983, 2023). "A recent study demonstrated that APOBEC3G down regulates miR-29 expression and hampers miR-29 activity in repressing MMP2, which promotes hepatic metastasis of colorectal cancer." (PMID 28903341, 2017). "Recent data suggest that APOBEC3G can promote liver metastasis in colorectal cancer, but its role in GBM is not clear." (PMID 28903341, 2017).
COVID-19 (5 papers, 2021 to 2024). A disease caused by infection with severe acute respiratory syndrome coronavirus 2. "APOBEC3G is significantly down-regulated in severe/critical COVID-19 patients and up-regulated in mild/moderate COVID-19 patients, compared with that in non-COVID-19 patients." (PMID 36551164, 2022). "Activation of ISGs appear to be beneficial in controlling SARS-CoV-2, but over-activation of proinflammatory cytokines and downregulation of certain ISGs (IFNA1, APOBEC3G, and FADD) and microRNAs (miR-155 and miR-130a) may be associated with progression to severe/critical COVID-19." (PMID 33780352, 2021). "We found a high expression of APOBEC3A, APOBEC3B, APOBEC3C, APOBEC3D, APOBEC3F, APOBEC3G and APOBEC3H in the classical, intermediate monocytes and NK cells of the COVID-19 patients compared to the healthy or recovered individuals." (PMID 36532041, 2022).
hepatocellular carcinoma (4 papers, 2010 to 2023). A malignant tumor that arises from hepatocytes. "However, another in vitro study found that high APOBEC3G expression reduced the migration ability of human hepatocellular carcinoma cells." (PMID 36204983, 2023). "However, recent studies demonstrated that in spite of the induction of APOBEC3G in hepatoma cells exposed to IFNs, the cytokine-mediated inhibition of HBV replication is not affected when the expression of APOBEC3G is suppressed by combining RNA interference and the Vif protein of HIV-1." (PMID 20957108, 2010).
melanoma (4 papers, 2020 to 2023). A malignant, usually aggressive tumor composed of atypical, neoplastic melanocytes. "APOBEC3G gene and protein expression was significantly more abundant in melanoma compared to adjacent normal tissues, and its higher expression was associated with longer overall and recurrence‐free survival." (PMID 36204983, 2023). "The prognostic significance of GBP2 and APOBEC3G in melanoma has also been backed up by other research investigations." (PMID 36211436, 2022). "We successfully separated the TCGA-melanoma samples into two subtypes on the basis of the expression of the ICD-related genes and developed a prognostic ICDRS involving 3 genes (i.e., GBP2, THBS4, and APOBEC3G) based on the DEGs between the two subtypes." (PMID 36211436, 2022).
multiple myeloma (4 papers, 2019 to 2023). "It has been shown that elevated APOBEC3G contributes to increased homologous recombination activity and uses increased DNA breaks to mediate genomic rearrangements in multiple myeloma (MM) cells, thereby affecting tumor progression." (PMID 37919386, 2023). "We investigated the role of APOBEC3G in MM and observed that A3G expression and APOBEC deaminase activity is elevated in myeloma cell lines and patient samples." (PMID 34625538, 2021).
bladder cancer (3 papers, 2019 to 2025). "Our present results warrant further analyses regarding the role of APOBEC3G in bladder cancer, which may be methodologically hampered due to challenging immunological differentiation between various members of the APOBEC family." (PMID 36204983, 2023). "While the roles of APOBEC3A and APOBEC3B in bladder cancer have not been functionally explored, transgenic overexpression of APOBEC3G in a BBN-induced carcinogen mouse model of bladder cancer has documented that APOBEC3G can shorten survival as well as drive genomic instability." (PMID 41390483, 2025).
glioma (3 papers, 2012 to 2023). A benign or malignant brain and spinal cord tumor that arises from glial cells (astrocytes, oligodendrocytes, ependymal cells). "APOBEC3G represents a potential molecular target for novel therapeutics that will improve the treatment outcome of glioma patients." (PMID 28903341, 2017). "APOBEC3G regulates cell invasion and silencing of this gene in GICs inhibits cell invasion and also glioma sphere initiation." (PMID 28903341, 2017). "To delineate the molecular mechanisms through which APOBEC3G regulates CD44+ glioma cell proliferation and migration, we investigated intracellular signaling pathways in APOBEC3G knockdown cells." (PMID 28903341, 2017). "To further understand the role of APOBEC3G in Smad2 deactivation in gliomas, we determined its role in mediating the expression of the Smad2-targeted genes Thrombospondin 1 (TSP-1), matrix metallopeptidase 2 (MMP2) and TIMP metallopeptidase inhibitor 1 (TIMP-1)." (PMID 28903341, 2017). "We further studied the invasion ability of glioma cells and performed matrigel transwell migration assays to demonstrate that knockdown of APOBEC3G decreased the number of cells that migrated to the other side of transwell by 50.8% in A172 cells (P < 0.01) and 49.1% in U343 cells (P < 0.01)." (PMID 28903341, 2017). "To assess the functional significance of the relative overexpression of APOEC3G in CD44+ mesenchymal glioma cells compared with CD44− glioma cells, we depleted APOBEC3G expression using lentivirus expressing shRNA directed against APOBEC3G in A172, U343, and GSC20 cells." (PMID 28903341, 2017). "Thus, anti-APOBEC3G therapy may synergize with radiotherapy and other current treatments to overcome the therapeutic resistance of gliomas." (PMID 28903341, 2017). "To validate the relationship between high levels of APOBEC genes and reduced survival in an independent dataset, we looked at the overexpression of APOBEC3G and APOBEC3C in gliomas in the REMBRANDT dataset." (PMID 22829908, 2012).
head and neck squamous cell carcinoma (3 papers, 2020 to 2025). A squamous cell carcinoma that arises from any of the following anatomic sites: lip and oral cavity, nasal cavity, paranasal sinuses, pharynx, larynx, and salivary glands. "Moreover, elevated APOBEC3G levels make cells more susceptible to cisplatin, thus potentially improving the prognosis of patients with head and neck squamous cell carcinoma (HNSCC)." (PMID 40704619, 2025).
ovarian carcinoma (3 papers, 2016 to 2023). A malignant neoplasm originating from the surface ovarian epithelium. "Other studies have associated APOBEC3G as a new biomarker in ovarian cancer prognosis in tumor-infiltrating T-lymphocytes." (PMID 37111415, 2023). "In ovarian carcinoma, the expression of APOBEC3G was positively correlated with T cell infiltration, expression of cytotoxic granzyme and perforin (GZMB and PRF1), and improved clinical outcome." (PMID 34307377, 2021). "The resulting two main clusters for ovarian cancer cell lines accentuate the expression differences for APOBEC3B, APOBEC3C, and APOBEC3G as well as of ID2 and ID3." (PMID 27527602, 2016). "Small molecules as agonists or antagonists, which are able to modulate specifically the APOBEC3G and APOBEC3B levels and activities, respectively, can be as well considered as starting points for further development of combinatorial drug applications in ovarian cancer." (PMID 27527602, 2016).
prostate carcinoma (3 papers, 2011 to 2015). A carcinoma that arises from epithelial cells of the prostate gland. "There is also a deficiency in the host restriction factor APOBEC3G in 22Rv1 cells and other prostate cancer cell line." (PMID 22615748, 2012). "Another factor that might account for the ready acquisition of XMLV and related gamma-retroviruses is low expression of APOBEC3G, which appears to be a common feature of prostate cancer cell lines and the MCF7 cell lines used here." (PMID 25912714, 2015).
serous ovarian carcinoma (3 papers, 2023 to 2024). "Notably, high expression of APOBEC3G, one of the APOBEC3 genes, has shown a strong correlation with T‐cell infiltration and improved outcomes in patients with high‐grade serous ovarian carcinoma." (PMID 38434763, 2024).
Co-infection (2 papers, 2016 to 2024). "This study suggests that APOBEC3G is a susceptibility gene for HIV-1/HBV co-infection mainly because of the HIV-1 mono-infection in a population from Burkina Faso." (PMID 27449138, 2016).
HCMV infection (2 papers, 2020 to 2023). "Latent HCMV infection has already been shown to downregulate APOBEC3G in CD34+ progenitor cells." (PMID 33679688, 2020).
measles (2 papers, 2019 to 2022). A highly contagious viral infection caused by the measles virus. "In this respect, it is important to note that APOBEC3G was previously found to target replication of other types of viruses, including mumps, measles, and respiratory syncytial viruses." (PMID 36142362, 2022). "Recently, we found that the cytidine deaminase APOBEC3G (A3G) inhibits measles (MV) replication." (PMID 30621148, 2019).
serous ovarian adenocarcinoma (2 papers, 2016). "Using a discovery cohort of 194 high‐grade serous ovarian adenocarcinoma (HGS‐OvCa) exomes, the results confirm the ability of the novel in silico approach used to identify changes in the preferred target motifs for AID, APOBEC3G, APOBEC3B, and ADAR1 during oncogenesis." (PMID 27485054, 2016).
breast tumors (1 paper, 2022). "In addition, we found that APOBEC3G was highly expressed in all inflammation tissues and was positively correlated with Treg cell immune infiltration in breast tumors." (PMID 35992864, 2022).
cervical cancer (1 paper, 2020). A primary or metastatic malignant neoplasm involving the cervix. "We found that the LOXL2-interference resulted in an increase in APOBEC3A, APOBEC3B, APOBEC3D, and APOBEC3G protein levels in the cervical cancer cells." (PMID 32211324, 2020). "Therefore, we also integrated the APOBEC family (APOBEC1 APOBEC3A, APOBEC3B, APOBEC3C, APOBEC3D, APOBEC3F, APOBEC3G, and APOBEC3H) mRNA expression of 176 core-set cervical carcinoma samples for multiplatform integrative analyses." (PMID 32211324, 2020).
Hepatitis (1 paper, 2024). Inflammation of the liver. "Conversely, other ISGs, including ISG20, IFI16, APOBEC3G, CXCL10, and CXCL11, which were predominantly expressed in T cells and nMacs, and upregulated during the hepatitis phase, showed a positive correlation with serum ALT levels, indicating their involvement in liver injury." (PMID 39135698, 2024).
influenza (1 paper, 2018). An acute viral infection of the respiratory tract, occurring in isolated cases, in epidemics, or in pandemics; it is caused by serologically different strains of viruses (influenzaviruses) designated A, B, and C, has a 3-day incubation period, and usually lasts for 3 to 10 days. "As anticipated, APOBEC3G was upregulated in the influenza-infected cells, and APOBEC3H expression also increased." (PMID 29654310, 2018).
lung carcinoma (1 paper, 2022). "In this study, we performed a comprehensive screening of radiosensitization targets in human lung cancer cell line A549 using an shRNA library and identified apolipoprotein B mRNA editing enzyme catalytic subunit 3G (APOBEC3G: A3G) as a candidate target." (PMID 35563460, 2022).
pancreatic adenocarcinoma (1 paper, 2022). "However, the role of APOBEC1, APOBEC3A, APOBEC3G and APOBEC3H in pancreatic adenocarcinoma is not clear, and related studies are very scarce, which motivated us to carry out relevant bioinformatics analysis." (PMID 36339709, 2022).
psoriasis (1 paper, 2018). An autoimmune condition characterized by red, well-delineated plaques with silvery scales that are usually on the extensor surfaces and scalp. "The pro-inflammatory environment of psoriasis results in an antiviral state and the increased expression of antiviral proteins, such as the cytidine deaminase APOBEC3G and phosphohydrolase SAMHD124." (PMID 29531256, 2018).
renal carcinoma (1 paper, 2020). A carcinoma arising from the epithelium of the renal parenchyma or the renal pelvis. "APOBEC3G, a member of the Apolipoprotein B mRNA editing enzyme-catalyzed polypeptide (APOBEC) family, was found to be overexpressed in renal carcinoma tissues and cell lines, consistent with our results." (PMID 33488680, 2020).